GAS2L2 (growth arrest specific 2 like 2)
Description:
Involved in the cross-linking of microtubules and microfilaments. Regulates microtubule dynamics and stability by interacting with microtubule plus-end tracking proteins, such as MAPRE1, to regulate microtubule growth along actin stress fibers. Enhances ADORA2-mediated adenylyl cyclase activation by acting as a scaffold to recruit trimeric G protein complexes to ADORA2A (By similarity). Regulates ciliary orientation and performance in cells located in the airway.
Synonyms: GAR17; CILD41
Tractability: Antibody: UniProt places it where antibodies can reach, with medium confidence; its Gene Ontology location is reachable by antibodies, with medium confidence. PROTAC: ubiquitination databases record sites on it.
Gene: Protein-coding gene on chromosome 17 (35,744,511 to 35,753,260, reverse strand). Ensembl gene ENSG00000270765.
Subcellular location: Cytoplasm, cytoskeleton; Cell membrane; Cytoplasm, cytoskeleton, stress fiber; Cytoplasm, cytoskeleton, cilium basal body
Gene Ontology:
Molecular function: protein binding; actin filament binding; cytoskeletal anchor activity; G-protein alpha-subunit binding; microtubule binding
Biological process: microtubule bundle formation; protein localization to microtubule plus-end; regulation of cilium beat frequency involved in ciliary motility; regulation of microtubule polymerization or depolymerization; actin crosslink formation; negative regulation of microtubule depolymerization; positive regulation of G protein-coupled receptor signaling pathway
Cellular component: actin filament; ciliary basal body; microtubule plus-end; cytoplasm; plasma membrane; stress fiber; cytoskeleton
Genetic constraint (gnomAD): Loss-of-function variants: 21 observed, 34.2 expected, observed/expected ratio (o/e) 0.61, 90% interval 0.44 to 0.88. The upper end of that interval is the gene's LOEUF score, 0.88, which puts it in group 3 of 6, group 1 being the genes least tolerant of losing a copy. Missense variants: 1,164 observed, 1,145.5 expected, observed/expected ratio (o/e) 1.02, 90% interval 0.97 to 1.07. Synonymous variants: 489 observed, 477.89 expected, observed/expected ratio (o/e) 1.02, 90% interval 0.95 to 1.1.
Gene-disease validity (ClinGen):
ClinGen rates the evidence that GAS2L2 causes each of these diseases.
ciliary dyskinesia, primary, 41 (autosomal recessive): Moderate.
Homologues: Orthologues: chimpanzee GAS2L2 (98% identical), macaque GAS2L2 (91% identical), dog GAS2L2 (76% identical), pig GAS2L2 (76% identical), rabbit GAS2L2 (71% identical), mouse Gas2l2 (67% identical), rat Gas2l2 (67% identical), Drosophila melanogaster jbug (23% identical). Paralogues in human: SPTBN2 (18% identical), SPTBN1 (17% identical), DST (17% identical), SPTB (17% identical), SPTBN4 (17% identical), FLNA (16% identical), MACF1 (16% identical), SYNE1 (16% identical), PLEC (16% identical), FLNC (15% identical), SPTBN5 (15% identical), SYNE2 (15% identical), and 24 more.
Diseases named in the same sentence as GAS2L2 in open-access papers:
GAS2L2 is named in the same sentence as 9 diseases in open-access papers, as found by Europe PMC text mining. Sharing a sentence is not in itself a finding about the gene and the disease. The quoted sentences say what the papers report.
primary ciliary dyskinesia (2 papers, 2021 to 2023). A rare, genetically heterogeneous, primarily respiratory disorder characterized by chronic upper and lower respiratory tract disease. "Discovery of new disease genes—Four genes, i.e., TTC12, GAS2L2, DNAH9 and DNAJB13, whose mutations are responsible for Primary Ciliary Dyskinesia (PCD) have been identified through molecular and cellular studies performed in the framework of the RaDiCo-DCP cohort." (PMID 34715889, 2021).
Breast invasive carcinoma (1 paper, 2021). "For instance, compared with normal tissues of TCGA‐BRCA (Breast invasive carcinoma), we observed a lower expression level of GAS2 and GAS2L2 genes (p < 0.001), but a high expression level of GAS2L3 (p < 0.001) in the tumor tissues." (PMID 33713047, 2021).
endometriosis (1 paper, 2025). The growth of functional endometrial tissue in anatomic sites outside the uterine body. "In contrast, some genes were significantly downregulated in endometriosis patients, among others KIF22, KIF25, GAS2L2, and HINT3." (PMID 41516028, 2025). "Furthermore, the identification of upregulated genes, such as SIRT1, SBDS, SRF, SPN, P2RX1, TEAD3, and SLITRK3, alongside downregulated genes, including KIF22, KIF25, GAS2L2, and HINT3, highlights a broad transcriptional reprogramming within endometriosis-affected tissues." (PMID 41516028, 2025).
glioma (1 paper, 2021). A benign or malignant brain and spinal cord tumor that arises from glial cells (astrocytes, oligodendrocytes, ependymal cells). "Similarly, the high expression of GAS2L2 was only associated with the clinical OS prognosis of glioma patients in the TCGA‐LGG project." (PMID 33713047, 2021). "We also analyzed the mutation status of GAS2, GAS2L1, GAS2L2, and GAS2L3 in the glioma samples of TCGA‐LGG/GBM or CGGA‐WEseq_286 project, respectively." (PMID 33713047, 2021). "Therefore, our findings did not provide strong evidence regarding the correlation between the expression of GAS2, GAS2L1, and GAS2L2 and the clinical prognosis of glioma cases." (PMID 33713047, 2021). "Herein, we first comprehensively explored the potential correlation between growth‐arrest‐specific two family genes (GAS2, GAS2L1, GAS2L2, GAS2L3) and gliomas by bioinformatics analysis and cellular experiments." (PMID 33713047, 2021). "Compared with GAS2, GAS2L1, and GAS2L2, there is a stronger correlation between GAS2L3 gene expression and glioma prognosis." (PMID 33713047, 2021). "In summary, compared with GAS2, GAS2L1, and GAS2L2, there is a stronger correlation between GAS2L3 gene expression and glioma prognosis." (PMID 33713047, 2021). "Apart from GAS2L3, we did not observe the strong evidence supporting the significant expression difference of the GAS2, GAS2L1, and GAS2L2 genes between glioma cases and negative controls." (PMID 33713047, 2021).
tumor (2 papers, 2021). "Additionally, more cell, animal and clinical sample‐based investigations are needed to further explore the potential role or clinical benefits of GAS2L1, GAS2L2 and GAS2L3 in the aetiology and pathogenesis of relevant diseases, such as tumours." (PMID 33103301, 2021).
cancer (1 paper, 2021). A tumor composed of atypical neoplastic, often pleomorphic cells that invade other tissues. "The rs12602590 polymorphism of GAS2L2 was reported to be linked to the pain flare and dexamethasone response of cancer patients with painful bone metastases who received palliative radiation therapy." (PMID 33103301, 2021). "A mis‐sense mutation site (R122Q/*/L) and a truncating mutation site (P409Lfs*92) of GAS2L2 were detected in six cancer cases." (PMID 33103301, 2021).
GAS2L2 also shares sentences with these, for which no sentence is quoted: ciliopathy (1 paper); Hydrolethalus (1); male infertility (1).